TAGLN (transgelin)
Description:
Actin cross-linking/gelling protein (By similarity). Involved in calcium interactions and contractile properties of the cell that may contribute to replicative senescence.
Synonyms: SM22-alpha; SM22; WS3-10; TAGLN1; SMCC; DKFZp686P11128; TGLN
Tractability: No criterion of Open Targets' tractability assessment is met for any kind of drug.
Gene: Protein-coding gene on chromosome 11 (117,197,509 to 117,207,464, forward strand). Ensembl gene ENSG00000149591.
Subcellular location: Cytoplasm
Subcellular location (Human Protein Atlas): Cytosol; Mitochondria; Microtubules; Nucleoplasm
Gene Ontology:
Molecular function: protein binding
Biological process: epithelial cell differentiation; muscle organ development
Cellular component: cytoplasm
Genetic constraint (gnomAD): Loss-of-function variants: 16 observed, 22.89 expected, observed/expected ratio (o/e) 0.7, 90% interval 0.47 to 1.06. The upper end of that interval is the gene's LOEUF score, 1.06, which puts it in group 4 of 6, group 1 being the genes least tolerant of losing a copy. Missense variants: 248 observed, 271.23 expected, observed/expected ratio (o/e) 0.91, 90% interval 0.82 to 1.02. Synonymous variants: 96 observed, 97.29 expected, observed/expected ratio (o/e) 0.99, 90% interval 0.84 to 1.17.
Homologues: Orthologues: chimpanzee TAGLN (100% identical), macaque TAGLN (99% identical), pig TAGLN (99% identical), guinea pig TAGLN (97% identical), mouse Tagln (97% identical), rat Tagln (97% identical), tropical clawed frog tagln (81% identical), zebrafish tagln (73% identical), zebrafish tagln2 (69% identical), Caenorhabditis elegans cpn-2 (39% identical), Drosophila melanogaster Chd64 (36% identical), Drosophila melanogaster Mp20 (36% identical), and 3 more. Paralogues in human: TAGLN3 (67% identical), TAGLN2 (65% identical), CNN3 (45% identical), CNN1 (40% identical), CNN2 (39% identical).
Diseases named in the same sentence as TAGLN in open-access papers:
TAGLN is named in the same sentence as 153 diseases in open-access papers, as found by Europe PMC text mining. Sharing a sentence is not in itself a finding about the gene and the disease. The quoted sentences say what the papers report.
colorectal cancer (35 papers, 2014 to 2025). A primary or metastatic malignant neoplasm that affects the colon or rectum. "While other members of the family have been associated with diseases such as asthma, TAGLN is more commonly associated with Colorectal Cancer, with expression being elevated in patients with advanced disease." (PMID 41146907, 2025). "Increased levels of TAGLN have also been associated to poor prognosis and metastasis in other types of cancer, such as esophageal, pancreatic, lung and colorectal cancers." (PMID 36990991, 2023). "Multiple studies in colorectal, gastric, pancreas, non–small cell lung cancer have shown increased TAGLN expression is associated with migration, invasion, and poor survival; however, others have suggested it is a tumor suppressor in colorectal cancer." (PMID 36222710, 2022). "MSI2, MACC1 and TAGLN were reported to be associated with ovarian cancer, colorectal cancer and esophageal cancer, respectively." (PMID 31640538, 2019). "Previous studies have suggested that transgelin expression is associated with cancer development and progression, but its specific role in colorectal cancer (CRC) remains controversial." (PMID 29416680, 2018). "Moreover, poor survival of patients with colorectal cancer has been associated with elevated levels of transgelin and tensin 1; siRNA of both these proteins decreases proliferation and invasion." (PMID 34203203, 2021). "Interestingly, we previously reported that the expression of the actin-binding protein, transgelin was up-regulated in colorectal cancer stroma and was associated with poor prognosis." (PMID 33297976, 2020). "However, contrary results from different independent laboratories showed that overexpression of TAGLN causes a poor prognosis in colon cancer in vivo and contributes to colorectal cancer progression and metastasis." (PMID 31591355, 2019). "However, other studies concluded that TAGLN is a tumor suppressor gene associated with a poor prognosis in colorectal carcinoma patients." (PMID 31591355, 2019). "Another example is, TAGLN, reported to be overexpressed in colorectal cancer which indeed showed strong overrepresentation in CRC and PDAC (Fig. EV4B,C)." (PMID 39558110, 2025). "The results demonstrated that one protein, transgelin, was down-regulated in mice with induced colorectal cancer." (PMID 41008635, 2025). "Recently, TAGLN was reported to be a poor prognostic factor in advanced stage colorectal cancer, promoting tumor growth and metastasis." (PMID 36990991, 2023). "TAGLN gene was also included in an autophagy-stroma gene signature which was an independent prognostic factor for colorectal cancer." (PMID 37296997, 2023). "Studies on TAGLN found that its imbalance can promote the development of rectal, breast, and colorectal cancers, and is considered to be a tumor suppressor." (PMID 37149635, 2023). "TAGLN has also been identified as a fibroblast-specific biomarker of poor prognosis in colorectal cancer (CRC) in a single-cell multiomics sequencing study, with 21 patients with CRC and 6 cancer-free individuals." (PMID 36990991, 2023). "The present study aimed to investigate the elusive expression pattern of CDC42, TAGLN, and GSN genes in patients with high and low-risk polyp samples, and also colorectal cancer patients and their adjacent normal tissues." (PMID 37365287, 2023). "Lastly, the study suggests the potential utility of the CDC42, TAGLN, and GSN genes as diagnostic or prognostic markers for colorectal cancer." (PMID 37365287, 2023). "Relevant studies have shown that TAGLN expression is significantly lower in the bladder, renal cell, and colorectal cancer tissues than the corresponding normal tissues." (PMID 35665757, 2022). "Transgelin (Tagln) is also a TGFβ signaling regulated gene and its upregulation predicts a poor overall survival outcome in colorectal cancer patients." (PMID 35565312, 2022).
colorectal cancer (continued). "The authors highlighted that the overexpressed BGN, RCN3, TAGLN, MYL9 and TPM2 in cancer-associated fibroblast as potential prognostic biomarkers for patients with colorectal cancers." (PMID 36172359, 2022). "Chrysin can directly act on the COMP/TAGLN interaction interface and inhibit mesenchymal transformation, thereby hindering the malignant progression of colorectal cancer." (PMID 32754278, 2020). "The correlation between the expression of COMP and TAGLN was analyzed by using the sequencing data from patients with colorectal cancer in The Cancer Genome Atlas (TCGA) database." (PMID 32754278, 2020). "Survival analysis revealed that the high expression of TAGLN suggested the poor prognosis of colorectal cancer." (PMID 32754278, 2020). "COMP is highly expressed in highly malignant colorectal cancer and positively correlated with TAGLN expression." (PMID 32754278, 2020). "Transgelin was related to lymph node metastasis in colorectal cancer with participation in regulation of the transcriptional program associated with the epithelial-to-mesenchymal transition." (PMID 33297976, 2020). "The role of COMP and TAGLN in colorectal cancer was fully described by combining bioinformatics analysis and functional and mechanistic studies." (PMID 32754278, 2020). "A biological laboratory study of Chrysin was conducted in vivo and in vitro to further study the inhibitory effect of Chrysin on colorectal cancer through the COMP/TAGLN complex." (PMID 32754278, 2020). "COMP and TAGLN showed significant co-localization at the colorectal cancer tissue levels ((Pearson's correlation = 0.9711)." (PMID 32754278, 2020). "An in vitro study declared that apigenin upregulated the expression of TAGLN in mitochondria to exert its anti-tumor growth and anti-metastasis effects in colorectal cancer." (PMID 31591355, 2019). "Other studies indicated that TAGLN exerts an anti-metastasis effect in colon and colorectal cancers." (PMID 31591355, 2019). "While some studies negatively correlated TAGLN expression with lymph node status in colon and prostate cancers, others found positive correlation in colorectal cancer." (PMID 26421063, 2015). "Contrary to our results, however, hypermethylation of TAGLN was found in hepatocellular and colorectal carcinoma." (PMID 25109740, 2014). "Moreover, the MALDI-TOF analysis showed that two different isoforms of transgelin were present in the colorectal cancer group." (PMID 41008635, 2025). "On the contrary, the levels of transgelin are elevated in colorectal cancer and ovarian cancer." (PMID 39676863, 2024). "Moreover, transgelin is an adverse prognostic factor of tumor growth and migration in colorectal cancer patients." (PMID 39676863, 2024). "High TAGLN levels were negatively associated with survival and disease-free survival in colon adenocarcinoma, whereas low levels were positively correlated with survival in patients with stage III colorectal cancer." (PMID 36990991, 2023). "The TAGLN, MYL9, and TPM2 were found to be over-expressed in fibroblasts from primary tumors compared to adjacent normal tissues and were associated with a poorer prognosis in the TCGA cohort of colorectal cancer." (PMID 34771544, 2021). "The exact expression pattern and molecular function of TAGLN in colorectal cancer is also unclear." (PMID 32754278, 2020). "Moreover, COMP was found for the first time to interact with TAGLN to promote the migration and invasion of colorectal cancer cells." (PMID 32754278, 2020). "In colorectal cancer, the high expression of TAGLN is positively correlated with poor prognosis." (PMID 32754278, 2020). "Recent reports have also highlighted the important role of TAGLN in colorectal cancer." (PMID 32754278, 2020). "In conclusion, our data demonstrate that the transgelin/TNS1 axis is activated in colorectal cancer, suggesting that it may serve as a potential therapeutic and prognostic biomarker for CRC." (PMID 29416680, 2018).
colorectal cancer (continued). "Here we sought to determine the role of transgelin more directly by determining whether experimental manipulation of transgelin levels in colorectal cancer (CRC) cells led to changes in metastatic potential in vivo." (PMID 26847345, 2016). "The promoter region of TAGLN, one of the strongest candidate genes among many probe sets, was previously found to be methylated in hepatocellular carcinoma and normal hepatocytes and was hypermethylated in colorectal carcinoma." (PMID 26421063, 2015). "In our study, some lncRNAs, such as the AL139147.1, AC090825.1, AC005726.2, AP001107.6, and AC107021.2, were related to the TAGLN, which could promote the metastasis of the advanced colorectal cancer or as potential molecular targets to prevent colorectal cancer progression." (PMID 38186577, 2023). "While our study's findings suggest the potential prognostic value of the CDC42, TAGLN, and GSN genes in colonic polyp lesions and colorectal cancer, it is essential to acknowledge certain limitations." (PMID 37365287, 2023). "In the context of colorectal cancer, the genes CDC42, TAGLN, and GSN have gained increasing recognition due to their significant involvement in key processes related to cancer progression and metastasis." (PMID 37365287, 2023). "BGN, RCN3, TAGLN, MYL9, and TPM2 were identified as fibroblast-specific biomarkers with a poor prognosis in colorectal cancer." (PMID 35785171, 2022). "Therefore, COMP/TAGLN may be a potential target for colorectal cancer therapy." (PMID 32754278, 2020). "Chrysin inhibited the EMT in colorectal cancer, and this mechanism was achieved by targeting the COMP/TAGLN complex." (PMID 32754278, 2020). "Finally, transgelin (TAGL), here identified for the first time with four different protein species, collectively down-regulated in colon cancer tissues, emerged as a top-ranked biomarker for colorectal cancer (CRC)." (PMID 32353950, 2020).
bladder cancer (19 papers, 2011 to 2025). "In bladder cancer, several studies demonstrated that high expression of transgelin is associated with poor prognosis, cancer progression, and aggressive pathological features." (PMID 35805203, 2022). "Our finding indicated that the expression of TAGLN was predominant in the cytosol and associated with F-actin during the ectopic overexpression of bladder carcinoma HT1376 cells." (PMID 31591355, 2019). "Based on this feature, TAGLN is widely considered to have tumor suppressor effects, and further studies have shown that TAGLN may not only serve as a potential diagnostic biomarker for bladder cancer (BCa), but may also be a promising therapeutic target." (PMID 41181151, 2025). "All these findings suggested that ACTA2, FLNA, TAGLN and TPM1 were potential diagnostic biomarkers for bladder cancer." (PMID 37274283, 2023). "The seed gene DMD seems more related to survival, while the transgelin gene TAGLN is closely connected to oncogenic transformation and, consequently, prognosis in bladder cancer patients." (PMID 36175974, 2022). "In bladder cancer, TAGLN can affect the upregulation of TGF-β-stimulated Slug and MMP14, and thus play a role in regulating EMT." (PMID 34552870, 2021). "In bladder cancer, TAGLN affects cell colony formation, cell migration, and invasion by regulating invadopodia formation and epithelial-mesenchymal transformation." (PMID 34552870, 2021). "A recent study found that transgelin is highly expressed in bladder cancer, and promotes EMT both in vivo and in vitro." (PMID 34830879, 2021). "Silencing of TAGLN2, a homologue of TAGLN, has been reported to significantly inhibit cell proliferation and increase apoptosis in bladder cancer." (PMID 34771544, 2021). "Meanwhile, a recent study showed that TAGLN was expressed in bladder carcinoma T24 and SW780 cells at the transcription and translation levels." (PMID 31591355, 2019). "The anti-tumorigenesis characteristics of TAGLN in bladder carcinoma cells was also demonstrated by an in vivo xenograft animal study." (PMID 31591355, 2019). "The normal primary bladder epithelial cells (HBdEC) presented far higher TAGLN protein levels in comparison to the bladder carcinoma T24 cells." (PMID 31591355, 2019). "In this study, we determined the expressions of TAGLN in both bladder carcinoma cells and bladder tissues, and examined the regulatory mechanisms and potential functions of TAGLN in bladder carcinoma cells." (PMID 31591355, 2019). "Results of RT-qPCR assays revealed that levels of TAGLN were higher in both HBdSMC and HBdEC cells than the bladder carcinoma cells." (PMID 31591355, 2019). "A previous study of prostates also identified TAGLN as a tumor suppressor gene in vivo and in vitro, and others found the same in bladder cancer, based on a gene profile analysis." (PMID 31591355, 2019). "Results from this study revealed that the ectopic overexpression of TAGLN decreased cell proliferation, invasion, and migration in bladder carcinoma cells in vitro, while the knockdown of TAGLN reversed the effects." (PMID 31591355, 2019). "In order to understand the subcellular location of TAGLN in the bladder carcinoma cells, we transiently overexpressed TAGLN in HT1376 cells." (PMID 31591355, 2019). "Our study is the first study providing direct evidence to demonstrate that TAGLN is an antitumor gene in the bladder carcinoma cells." (PMID 31591355, 2019). "In vitro, TAGLN knockdown enhanced cell proliferation and invasion, while overexpression of TAGLN had the inverse effects in bladder carcinoma cells." (PMID 31591355, 2019).
bladder cancer (continued). "The Matrigel invasion assays showed that 8301-TAGLN cells expressed markedly lower invasive capacity than 8301-DNA cells, while the knockdown of TAGLN in bladder carcinoma TSGH-8301 cells enhanced cell invasion." (PMID 31591355, 2019). "This study illustrated that protein and mRNA levels of TAGLN are higher in human normal primary bladder epithelial cells (HBdEC) than in bladder carcinoma cells." (PMID 31591355, 2019). "TAGLN is expressed at low levels in bladder carcinoma and prostate cancer, but potentiates the proliferation and growth of other cancer cells, which suggests that TAGLN might represent an early event in tumor progression." (PMID 38087889, 2024). "However, additional research has shown that TAGLN has carcinogenic properties and is overexpressed in bladder cancer, promoting tumor progression and metastasis." (PMID 37274283, 2023). "Some studies have also shown that Transgelin gene expression is upregulated in bladder cancer." (PMID 34552870, 2021). "Furthermore, the study also found that there was a significant correlation between the EMT transcription factor Slug with transgelin in bladder cancer." (PMID 34830879, 2021). "The paradox is potentially resolved if timing and transient transgelin expression is important in the progression of bladder cancer as it may be in the formation of a blastema." (PMID 34518542, 2021). "Also, CNN1, TAGLN, and TMP2 were already characterized as prognostic molecular markers for bladder cancer with higher expression associated with lower survival." (PMID 34261540, 2021). "TAGLN seems to function as a tumor suppressor gene in bladder carcinoma cells." (PMID 31591355, 2019). "However, previous studies indicated that TAGLN is one of the common differentially-expressed genes which is significantly decreased in bladder cancer compared with normal bladder tissues." (PMID 31591355, 2019). "Our study presents the tumor suppressor characteristics of TAGLN in bladder cancer, both in vitro and in vivo, and agrees with the concept of that the role of transgelin-2 in tumor development might be contradictory to the role of TAGLN." (PMID 31591355, 2019). "Although studies in bladder cancer suggested that TAGLN was one of common differentially-expressed genes, significantly decreased in cancer compared with normal tissues, the precise functions and regulatory mechanisms of TAGLN in bladder carcinoma cells are still unexplored." (PMID 31591355, 2019). "We compared expressions of TAGLN in human bladder carcinoma cells to the normal human bladder tissues to determine the potential biological functions and regulatory mechanisms of TAGLN in bladder carcinoma cells." (PMID 31591355, 2019). "The results of the analysis showed that seven genes (VCL, FLNA, THBS1, TAGLN, ACTA2, COL6A2, and CALD1) were significantly correlated (P < 0.05) with the prognosis of bladder cancer patients, and these genes were included in the subsequent in-depth study." (PMID 41181151, 2025). "Consistent with our study, previous studies have reported these key genes (TAGLN, CNN1, ACTC1, LMOD1) play important roles in bladder cancer." (PMID 38144520, 2023). "Earlier investigations have shown that TAGLN is an antitumor gene with decreased expression in BLCA, and its overexpression inhibits bladder cancer cell growth, invasion, and migration." (PMID 37274283, 2023). "Next, we performed the survival analysis of these eight genes (ACTA2, CDH1, CCNB1, FLNA, MCM5, MAD2L1, TAGLN and TPM1) in bladder cancer." (PMID 37274283, 2023). "Bioinformatic analyses demonstrated that the expression of ACTA2, FLNA, TAGLN and TPM1 in bladder cancer was markedly downregulated relative to nearby normal tissue." (PMID 37274283, 2023).